IL1B (interleukin 1 beta)
Diseases named in the same sentence as IL1B in open-access papers (continued):
Sharing a sentence is not in itself a finding about the gene and the disease.
preeclampsia (continued). "The increased decidual NLRP3 and IL-1β expression associated with preeclampsia with normal fetal growth could not be explained by differences in decidual leukocyte and trophoblast density." (PMID 33117348, 2020). "At the same time, the upregulation of the proinflammatory cytokines IL-1β and TNF-α in the serum of preeclampsia patients suggested the activation of systemic inflammation in preeclampsia patients." (PMID 36310595, 2022). "Inflammatory markers such as cytokines (IL-1b, IL-6, TNF-α, INF-γ) are involved in the pathogenesis of preeclampsia." (PMID 33809556, 2021). "However, it has been suggested that the pro-inflammatory cytokines TNF-α and IL-1β are involved in IUGR and preeclampsia." (PMID 39065188, 2024). "In early pregnancy (10-14 weeks), IL-1β significantly differs between women who develop preeclampsia and those who remain healthy (data not in tables as concentration was presented as a multiple of the gestational median value (MoM) ratio)." (PMID 33680514, 2021). "Furthermore, blood pressure, a clinical parameter used to identify the onset of preeclampsia, was negatively correlated with GCM1 and positively correlated with IL-1β expression." (PMID 34576036, 2021). "For instance, in the plasma of mothers with preeclampsia, concentrations of IL-6, but not TNFα or IL-1β, were higher than those reported in normal patients." (PMID 34696359, 2021). "Further, the IL-1β expression intensity in trophoblast-containing decidual areas was significantly higher in preeclampsia without FGR compared to preeclampsia with FGR (P = 0.021)." (PMID 33117348, 2020). "Interestingly, the most pronounced increase in fold change was observed for the pro-inflammatory cytokines IL-1β, IL-8 and for TLR3, which are key mediators of inflammation in preeclampsia." (PMID 31991780, 2020). "Preeclampsia without FGR was associated with increased trophoblast dependent NLRP3 and IL-1β expression, particularly in the decidual areas of trophoblast and leukocyte proximity." (PMID 33117348, 2020). "Levels of TNF-α, IL-1β, and IL-6 were increased but IL-10 was decreased in culture medium of monocytes from women with preeclampsia compared with those from nonpregnant and normotensive pregnant women (all p < 0.01)." (PMID 31138166, 2019). "In the present study, we proposed to determine the concentration of eHsp‐60, ‐70, IL‐1β and TNFα in the serum of pregnant patients with 34 weeks of gestation with and without clinical evidences of preeclampsia (PE)." (PMID 30133944, 2018). "However, preeclamptic placentas secrete higher levels of IL1β into the maternal circulation and key components of the inflammasome including ASC, cleaved caspase-1, GSDMDNT, and HMGB1 are increased in the placenta from women with preeclampsia." (PMID 37292200, 2023). "A closer look at decidual tissue with trophoblast and maternal leukocytes in proximity showed that the expression intensity of NLRP3 and IL-1β was significantly increased in preeclampsia without FGR compared to normal pregnancies (NLRP3 P = 0.017 and IL-1β P = 0.031)." (PMID 33117348, 2020).
silicosis (57 papers, 2010 to 2026). Silicosis is a respiratory disease caused by breathing in (inhaling) silica dust. "TNF a classical pro-inflammatory cytokine, stimulates fibroblasts proliferation and interacts with other inflammatory mediators, such as IL-1β, IL-6, and IL-8, to modulate immune responses and inflammatory reactions which are associated with silicosis." (PMID 40470053, 2025). "Studies have shown an association between IL1B gene polymorphism and an increased risk of silicosis." (PMID 38515835, 2024). "IL-1β has also been implicated in the pathophysiology of silicosis in both humans and animal experimental studies." (PMID 36311760, 2022). "NLRP3 and its downstream factors, caspase-1, IL-1β, and IL-18, were greatly expressed in the lung tissue of rats with silicosis, while the inhibition or deficiency of NLRP3 alleviated EMT in lung epithelial cells or inflammation in macrophages." (PMID 34360876, 2021). "Normally under stringent control in physiological conditions, IL-1β dysregulation has been shown to underlie a diverse range of diseases including Alzheimer’s disease, silicosis and rheumatoid arthritis." (PMID 27108091, 2016). "NLRP3 inflammasome activation and resultant IL-1β production by AMs is recognized as a significant mechanism underlying silicosis." (PMID 26913035, 2016). "In this case-control study, 5 SNPs in Nalp3, IL-1β, and caspase-1 genes were evaluated to define the risk of silicosis in a Chinese population." (PMID 26496436, 2015). "In silicosis, IL-1β has been implicated to participate in the processes of silica-induced pulmonary inflammation and fibrosis." (PMID 26496436, 2015). "To elucidate the underlying mechanisms of IL-1β and IL-17 in silicosis, we used anakinra and an anti-IL-17 monoclonal antibody (mAb) to block the receptor of IL-1β (IL-RI) and IL-17, respectively, in a mouse model of silicosis." (PMID 25091058, 2014). "The quartz-induced NALP3 activation and subsequent IL-1β release has recently been more directly linked to the development of silicosis upon chronic exposure." (PMID 22882971, 2012). "Therefore, we performed this meta-analysis to precisely evaluate the association between the IL-1α +4845G/T, IL-1β +3953C/T, IL-1RA +2018T/C, IL-1β -511C/T, IL-6 -634C/G, IL-6 -174G/C, and IL-17A -832A/G polymorphisms and silicosis susceptibility." (PMID 40182855, 2025). "Moreover, the characteristic up-regulation in IL-1β and IL-18 inflammatory cytokines associated with silicosis was also substantially mitigated in macrophages under Tet treatment." (PMID 34417574, 2022). "Also, SiO2 induced macrophage senescence and silicosis in lung tissue, both of which were accompanied by increased fibrosis-associated factors (IL-1β, IL-6, TNF, and TGF-β1) and MMPs (MMP2, MMP9 and MMP12)." (PMID 35959439, 2022). "Stratification analysis for associations between genotypes of IL-1β and the risk of silicosis." (PMID 26496436, 2015). "In order to investigate the interactions of genetic polymorphisms of Nalp3, caspase-1, and IL-1β with occupational dust exposure and the joint effects on the risk of silicosis, we conducted a case-control study of a large cohort of workers in a large iron mine." (PMID 26496436, 2015). "Notably, a persistent overproduction of the pro-inflammatory cytokine IL-1β has been linked to silicosis." (PMID 22882971, 2012). "In addition, the importance of IL-1β has also been implicated in clinical patients, and IL-1 gene polymorphism may confer an increased risk for the development of silicosis." (PMID 35401236, 2022). "Therefore, we hypothesized that genetic polymorphisms in Nalp3, caspase-1, and IL-1β may affect an individual’s susceptibility to silicosis." (PMID 26496436, 2015). "In mouse models of silicosis, elevated and persistent expression of IL-1β precedes the development of fibrosis, suggesting a critical role for IL-1β in disease progression." (PMID 40119408, 2025).
silicosis (continued). "A 2015 case published in the American Thoracic Society explored the use of anakinra to inhibit IL-1β in a patient with silicosis after seven years of exposure." (PMID 40438828, 2025). "Coincident with earlier findings, BIC suppressed TGF-β1 expression in BALF, serum, and lung tissues in our silicosis rat model, while the three other cytokines examined (IL-1β, IL-6, and TNF-α) were only decreased in BALF and lung tissue and not in serum." (PMID 39060930, 2024). "The Th17 response is key to promoting silicosis inflammation and fibrosis by affecting the homeostasis of Th cell-mediated immune responses and increasing the production of IL-22 and IL-1β." (PMID 38515835, 2024). "IL-17 modulates the differentiation of Tregs in the early phase of silicosis and promotes the Th1/Th2 immune response, thus influencing silica-induced lung inflammation and fibrosis by regulating the production of IL-22 and IL-1β." (PMID 38515835, 2024). "In the early stages of silicosis, M1 macrophages are stimulated, which promotes inflammation primarily through the production of the pro-inflammatory cytokines IL-1β and IL-6." (PMID 38515835, 2024). "The importance of IL-1β in silicosis has been demonstrated in both the inflammatory and fibrotic stages." (PMID 38515835, 2024). "The excessive secretion of IL-1β can aggravate silicosis, whereas its neutralization or knockout can reverse the progression of the disease." (PMID 38515835, 2024). "In a rat model of silicosis, silica was shown to activate the NLRP3 inflammasome and release of proinflammatory IL-1β, basic fibroblast growth factor, and high mobility group protein B1, resulting in silicosis." (PMID 36669831, 2023). "Patients with silicosis seem to have a chronic inflammatory process that is consistent with the augmented levels of some pro-inflammatory cytokines, i.e., IL-1β, IL-6, IL-7, IL-8, IL-16, IL-17A, IL-33 and TNF-α were observed in this work." (PMID 36675056, 2023). "The NLRP3-mediated production of IL-1β has a critical role in acute lung injury and is crucial in the development of particle-induced lung inflammation and fibrosis, i.e. silicosis." (PMID 37864207, 2023). "Clinical syndrome acute silicosis is characterised by rapid immune cell influx into the exposed lung and production of proinflammatory cytokines, including IL‐1β and chemokines." (PMID 37360982, 2023). "IL-1β is a cytokine derived from the mononuclear phagocyte system and plays an important role during silicosis." (PMID 35401236, 2022). "BALF from silicosis mice treated with clodronate liposome showed decreased IL-1β and IL-18 production." (PMID 36459518, 2022). "Taken together, these data demonstrated that Caspase-1/Gsdmd and Caspase-8/Gsdme both mediated IL-1β maturation and secretion in silicosis." (PMID 36459518, 2022). "In agreement with Szapiel scores, we found that both mRNA levels and protein concentration of IL-1β and IL-6 were all increased in silicosis mice, but were decreased in that of the Tet-treated silicosis mice." (PMID 34417574, 2022). "Increasing evidence highlights the proinflammatory cytokines IL-1β and IL-18 as key drivers in the development of silicosis." (PMID 35130879, 2022). "As previously shown, the deficiency of Nlrp3/Caspase-1/Gsdmd pathway cannot block silicosis, suggesting that IL-1β has a more fundamental role in silicosis." (PMID 36459518, 2022). "In silicosis, IL-10 is elevated but has a dual effect: on one side, IL-10 limits the amplitude of the inflammatory response by suppression of the production IL-1β, IL-6 and TNF-α in monocytes and macrophages." (PMID 36672608, 2022). "It has been recognized that silica-activated AMs release many cytokines, like TNF-α, interleukin-1β (IL-1β), and IL-6, etc., which is the basis of silicosis fibrosis." (PMID 34360876, 2021). "In fact, we observed increased IL‐10 levels in the lung tissue of Silicosis‐MT group animals, while there was a significant reduction in IL‐1β and TGF‐β." (PMID 32538526, 2020).
silicosis (continued). "In AMs from observers and silicosis patients, we found that the concentrations of IL-1β, IL-6, and TNF-α were significantly higher in the presence of LPS than those in the absence of LPS (P < 0.01)." (PMID 33817248, 2020). "In the context of silicosis, the lysis of alveolar macrophage releases cellular components into the extracellular environment, including IL-1β, promoting the recruitment of inflammatory cells into alveoli and endothelial walls." (PMID 32256366, 2020). "The secretion of TNF-α, IL-6, TGF-β1, and ox-LDL was increased in patients with silicosis in comparison to controls, except for IL-1β." (PMID 32351319, 2020). "Notably, overproduction of IL-1β has been linked causatively to silicosis and reduction of silicosis in vivo has been observed upon treatment with an IL-1 receptor antagonist, as well as in IL-1β knockout mice; suggesting that IL-1β is a key mediator of particle-induced inflammation." (PMID 27108091, 2016). "In this study, we evaluated 2 SNPs in IL-1β (-580C>T and Ex5+14C>T) and their relationships with silicosis." (PMID 26496436, 2015). "Phagocytosis of silica particles leads to NLRP3-inflamassome complex activation through lysosomal enzymes, culminating in IL-1β secretion, which participates in the acute and fibrotic processes of silicosis." (PMID 25310682, 2014). "The modest difference in Th1 responses between the anakinra + silica group and the saline + silica group demonstrated the minor contribution of IL-1β in the Th1 response during the lung inflammation of silicosis." (PMID 25091058, 2014). "Our previous study and the results presented here demonstrate that IL-1β can modulate the Th17 response in the inflammatory stage of silicosis." (PMID 25091058, 2014). "We then examined IL-1β protein expression from the supernatants of cultured alveolar macrophages isolated from our mouse model of silicosis." (PMID 25091058, 2014). "We also identified positive feedback between IL-1β and the Th17 response in our mouse model of silicosis." (PMID 25091058, 2014). "To investigate the underlying mechanism of IL-1β regulating Th17 cell differentiation in silicosis, we disabled silica-induced IL-1β using anakinra (1 mg/mouse)." (PMID 25091058, 2014). "Reduction of experimentally-induced silicosis has been observed upon treatment with IL-1 receptor antagonists as well as in IL-1β knockout mice, confirming IL-1β as a key inflammatory regulator." (PMID 22882971, 2012). "Activated Caspase-1 triggers the cleavage of proinflammatory cytokines, interleukin 1-beta and interleukin 18 for subsequent activation and secretion, which is likely to be part of the pathway leading to silicosis." (PMID 21311600, 2011). "The acute inflammatory cytokines Interleukin-1 beta (IL-1β) and Tumor Necrosis Factor alpha (TNFα) are prime examples and potent inducers of NF-κB themselves, and are known to be involved in silicosis." (PMID 20492675, 2010). "TNFα and IL-1β are considered important factors in the development of silicosis and are well-known inducers of NF-κB in various cell types." (PMID 20492675, 2010). "Another study discovered no obvious association between the IL-1β -511 variant and silicosis in the Chinese population." (PMID 40182855, 2025). "IL-1RA is an inhibitor of pro-inflammatory IL-1 and has been proposed as a good biomarker candidate for disease progression due to the increase in its levels as silicosis stages progress, which could be indicative of a mechanism to balance the effect of IL-1β." (PMID 41008784, 2025). "Moreover, the expression of silicosis related cytokines (IL-1β, IL-6, TNF-α, and TGF-β1) in BALF was further detected using ELISA." (PMID 39060930, 2024). "The role of IL-18 in silicosis is less well established than of IL-1β." (PMID 37864207, 2023). "Besides IL-1β, tumor necrosis factor α (TNFα) is the other critical early pro-inflammatory cytokine for the development of acute lung injury and silicosis." (PMID 37864207, 2023).
silicosis (continued). "In human plasma/serum, TNF-α levels in patients with silicosis or IL-1β, IL-6 and TNF-α in CWP patients have also been reported to be increased compared to control groups and even between simple pneumoconiosis and PMF groups, in accordance with the results in the present study." (PMID 36675056, 2023). "Notably, research in silica-induced animal models has firmly demonstrated that IL-1β secretion exacerbates silicosis, whereas its neutralization can reverse this disease." (PMID 34417574, 2022). "Furthermore, we found that in addition to Caspase 1, Caspase-8 cleaved IL-1β in silicosis, explaining why Caspase-1-/- mice also suffered from silicosis." (PMID 36459518, 2022). "Given the sound inhibitory effects of Tet against IL-1β, it is reasonable to speculate that the effectiveness of Tet treatment against silicosis is likely mediated by suppressing activation of the NLRP3 inflammasome." (PMID 34417574, 2022). "Substantial evidence supports that macrophages stimulated with silica exhibit high levels of IL-1β and that silica-induced fibrosis does not develop in IL-1R-deficient silicosis mice." (PMID 34417574, 2022). "It has been demonstrated that IL-1β secretion aggravated silicosis, neutralization, and blocking of IL-1β, which could reverse silicosis." (PMID 35401236, 2022). "Notably, RAB20 deficiency was associated with significantly higher concentrations of IL-1β and slightly higher concentrations of IL-18 in the BALF when compared to WT mice established with silicosis." (PMID 36131930, 2022). "Moreover, multiple studies have reported that Tet has the strong potential to inhibit the release of inflammatory cytokines, especially IL-1β, which greatly contributes to the pathogenesis of silicosis." (PMID 34417574, 2022). "PLS-DA of silicosis patients in our study, further documented the connections between the outcome of silicosis and cytokine predictors: Th1/Th2 pro-inflammatory IL-6, IL-1β and IFN-γ, which were significantly elevated in silicosis patients when compared to controls." (PMID 36311760, 2022). "Moreover, besides its direct effect, IL-1β can indirectly affect silicosis by acting on its downstream mediators." (PMID 35401236, 2022). "Macrophages play a crucial role in the pathophysiology of silicosis by secreting pro-inflammatory mediators, such as IL-1β, TNF-α, IL-6, MIP-1, and MIP-2, as well as growth factors and fibrogenic mediators, which lead to fibroblast activation and collagen deposition." (PMID 29126438, 2017). "The distributions of -580C>T and Ex5+14C>T polymorphisms in IL-1β were not different between patients with silicosis and subjects in control group." (PMID 26496436, 2015). "The Th17 response could induce lung inflammation during the pathogenesis of silicosis by regulating the homoeostasis of the Th immune responses and affecting the production of IL-22 and IL-1β." (PMID 25091058, 2014). "IL-1β and NO mediate apoptosis and inflammation in murine silicosis." (PMID 25299237, 2014). "IL-17 may promote lung inflammation by modulating the differentiation of Th1 and regulatory T cells (Tregs) and by regulating the production of IL-22 and IL-1β during the lung inflammation of silicosis." (PMID 25091058, 2014). "Therefore, it is possible that cathepsin Z’s contribution to inflammation in the mouse model of silicosis may involve both IL-1β generation and other inflammatory processes." (PMID 34864055, 2022). "Therefore, there exists a compensatory mechanism in which Caspase-8 mediates IL-1β maturation in the absence of Caspase-1 activity, explaining why Caspase-1 deficiency failed to protect mice from silicosis." (PMID 36459518, 2022). "In light of previous findings that Tet showed high affinity binding to alveolar macrophages and strongly inhibited production of IL-1β in macrophages, we thus speculated that the attenuation of silicosis by Tet might be ascribed to upstream blockade or inhibition of IL-1β and/or NLRP3 inflammasome." (PMID 34417574, 2022).